RNU6-1190P (RNA, U6 small nuclear 1190, pseudogene)
Gene: Small nuclear RNA gene on chromosome 5 (37,619,985 to 37,620,088, reverse strand). Ensembl gene ENSG00000222743.
Homologues: Orthologues: chimpanzee U6 (99% identical), macaque U6 (96% identical), mouse Gm24612 (87% identical), pig U6 (86% identical), guinea pig U6 (76% identical). Paralogues in human: RNU6-1152P (92% identical), RNU6-1019P (91% identical), RNU6-41P (91% identical), RNU6-1060P (90% identical), RNU6-15P (90% identical), RNU6-19P (90% identical), RNU6-211P (90% identical), RNU6-31P (90% identical), RNU6-12P (89% identical), RNU6-13P (89% identical), RNU6-166P (89% identical), RNU6-25P (89% identical), and 1289 more.